DPYSL2 (dihydropyrimidinase like 2)
Diseases named in the same sentence as DPYSL2 in open-access papers (continued):
Sharing a sentence is not in itself a finding about the gene and the disease.
tumor (27 papers, 2003 to 2025). "At the same time, numerous studies have demonstrated that phosphorylation of DPYSL2 and DPYSL2 is associated with drug resistance and tumor metastasis." (PMID 37409245, 2023). "Numerous reports have recently implicated DPYSL2 phosphorylation in the development of drug resistance and tumor metastasis, but there are a few reports on the involved mechanisms." (PMID 34517904, 2021). "Herein, we analyzed associations among DPYSL2 expression, tumor purity, and immune infiltration in the online tool TIMER." (PMID 34517904, 2021). "Dihydropyrimidinase like 2 (DPYSL2) has been linked to tumor metastasis." (PMID 34517904, 2021). "The association of DPYSL2 expression with LUAD tumor purity was revealed." (PMID 34517904, 2021). "Abdominal imaging showed that mice in the DPYSL2 control group had a higher tumor burden than those in the DPYSL2‐sh1 and DPYSL2‐sh2 groups." (PMID 36621846, 2023). "DPYSL2 is involved in tumor metastasis and has been elevated in smokers with COPD compared to never-smokers." (PMID 37821974, 2023). "The six key-gene signature (ADRB2, DPYSL2, IL7R, LIMCH1, PIK3R1 and SOX2) has been shown to be associated with metastasis and progression of many tumor types through molecular experiments." (PMID 38057344, 2023). "DPYSL2 is related to the mTOR signaling pathway; mTOR, as a central regulator of proliferation signal transduction, is an ideal target for tumor treatment." (PMID 35051904, 2022). "Herein, we assessed DPYSL2 expression in various tumor types via online databases such as Oncomine and Tumor Immune Estimation Resource (TIMER)." (PMID 34517904, 2021). "We also observed that DPYSL2 promoted cell proliferation, colony formation, migration, and invasion in vitro, as well as tumor formation and lung metastasis in vivo." (PMID 34295887, 2021). "Taken together, these findings indicate that DPYSL2 will likely become a new tumor marker and immunotherapy target in LUAD." (PMID 34517904, 2021). "We found that the nude mice transplanted with DPYSL2-overexpressing 5637 cells had significantly greater tumor mass and more metastatic nodules in the lungs than those transplanted with control cells." (PMID 34295887, 2021). "DPYSL2 undergoes dynamic phosphorylation changes in response to contact inhibition-induced quiescence and hyperphosphorylation of DPYSL2 occurs in a tumor." (PMID 23667495, 2013). "Additionally, deletion of the DPYSL2 gene in cancer cells resulted in a significant reduction in their migration and invasiveness, as well as tumor progression and metastasis." (PMID 40869314, 2025). "However, we found a correlation between the concentrations of LP-PLA2 and DPYSL2 and tumor size (in the GBM and brain metastases groups)." (PMID 40869314, 2025). "The expression level of DPYSL2 varies depending on the tumor type." (PMID 40869314, 2025). "DPYSL2 concentrations were also correlated with tumor size in both of these patient groups." (PMID 40869314, 2025). "Moreover, DPYSL2 is associated with LUAD immune cell molecular markers, implying that DPSYL2 has a role in tumor immune regulation in LUAD." (PMID 34517904, 2021). "These implicate DPYSL2 in tumor metastasis and drug resistance is complex." (PMID 34517904, 2021). "The present findings demonstrate that a correlation exists between DPYSL2 expression and neutrophils, macrophages, CD4+ T cells, and dendritic cells in the tumor microenvironment of LUAD." (PMID 34517904, 2021). "Interestingly, tumor size was strongly positively correlated with Lp-PLA2 and DPYSL2 concentrations in the GBM and brain metastases groups." (PMID 40869314, 2025). "Hence, we hypothesized that DPYSL2 inhibits the progression of LUAD through immune activation and response during the tumor process." (PMID 34517904, 2021). "Moreover, we have uncovered new genes affected by frameshift MSI events in MSI-prone tumours as well as in tumour types not frequently affected by MSI (for example, FAM129A, GMIP and NEK3 in BRCA, and DPYSL2 and ALPK2 in OV)." (PMID 28585546, 2017).
neurodegenerative disease (18 papers, 2014 to 2024). A disorder of the central nervous system characterized by gradual and progressive loss of neural tissue and neurologic function. "The role of DPYSL2, encoding Collapsin Response Mediator Protein 2 (CRMP2), in CNS injury and neurodegenerative diseases has been increasingly elucidated through genome-wide association studies (GWAS)." (PMID 39532785, 2024). "Several proteins were associated with neurodegenerative diseases, DPYSL2 and TPI1 were related to AD, UCHL1 was linked to PD, whereas ALDH was related to AD and PD." (PMID 27857231, 2016). "The synaptic protein CRMP2 (also referred as DPYSL2) is a key regulator of neuronal axon guidance and synaptogenesis whose dysregulation contributes to neuronal loss in neurodegenerative diseases by an unknown mechanism." (PMID 37030595, 2023).
neurological disorders (17 papers, 2014 to 2025). "DPYSL2 has emerged as a potential drug target for treating neurological diseases." (PMID 36621846, 2023). "Some downregulated proteins such as DPYSL2, TPI1, ALDH, and UCHL1 were found to play critical roles in the neurological disease and PSMA1, PSMA3, PSMC2, PSMD11, and UCHL1 in protein homeostasis." (PMID 27857231, 2016).
DPYSL2 also shares sentences with these, for which no sentence is quoted: epilepsy (9 papers); Cerebral ischemia (8); ischemia (8); Parkinson disease (6); psychiatric disorder (6); Anxiety (5); brain injury (5); Cognitive impairment (5); ovarian carcinoma (5); bipolar disorder (4); dementia (4); infection (4); Insulin resistance (4); ischemic stroke (4); memory impairment (4); neuropathic pain (4); Obesity (4); cognitive decline (3); colon carcinoma (3); diabetes (3); encephalitis (3); Hyperglycemia (3); metabolic disorders (3); multiple sclerosis (3); Stroke (3); T-lymphoma (3); Atrophy (2); autoimmune disease (2); encephalomyelitis (2); experimental autoimmune encephalomyelitis (2).
A further 67 diseases each share a sentence with DPYSL2 in 2 papers or fewer.